AGO2 (argonaute RISC catalytic component 2)
Diseases named in the same sentence as AGO2 in open-access papers (continued):
Sharing a sentence is not in itself a finding about the gene and the disease.
viral infection (continued). "The virus‐induced increase in expression of AGO2 and AGO5 in cassava is similar to that in N. benthamiana, in which Potato virus X infection increases AGO5 expression and AGO5 acts synergistically with AGO2 to suppress virus infection to a greater degree than the other AGO proteins." (PMID 28494519, 2018). "It is unclear how prevalent or virulent these viral infections are and future studies are needed to elucidate whether downregulation of Ago2 or Dcr2 affects the ability of WCR to defend against infections such as those caused by these viruses." (PMID 29267401, 2017). "It is possible that reduced Dcr2 or Ago2 expression in WCR may impair its ability to resist viral infection and may result in reduced fitness, if such infection is virulent." (PMID 29267401, 2017). "The antiviral activity of Ago-30, Ago-16 and Ago-68 (in case of viral infection) is in line with previous reports showing that mosquito/fly Ago-2 is involved in the antiviral RNAi response and phylogenetic analysis indicates that Ixodes Ago-30, Ago16 and Ago-68 are homologous to Ago-2 of insects." (PMID 25053841, 2014). "The hypersensitivity to viral infections of AGO2 mutant flies and of AGO2 knockdown mosquitoes provides genetic support for this hypothesis." (PMID 22916019, 2012). "In summary, robust suppression of viral infection can only be achieved by completely complementary siRNA bound Ago-2-mediated target cleavage and miRNA mediated translational repression/mRNA destabilization or other Ago proteins appear to have no role in the anti-flaviviral RNAi." (PMID 22102908, 2011). "Collectively, the available evidence suggests that circRNAs may be degraded by GW182 (a crucial component of the P-body and RNAi machine), RNase L in cells upon poly(I:C) treatment or viral infection, or by interacting with miRNAs in an Argonaute 2 (Ago2)-dependent manner." (PMID 40296024, 2025). "The virus infection intensity-dependent mortality was then confirmed through injection of different titers of MAYV into Ago2−/− mutants where a higher titer of MAYV led to higher mortality of Ago2−/− mutants." (PMID 37723154, 2023). "Similarly to the experimental schedule followed in the previous section, we wanted to check whether the effects of AGO2 inactivation could also be appreciated in viral infections launched with wt PLPV." (PMID 34623234, 2021). "However, the involvement of Vago through Dcr2 activity are an unlikely explanation for the observed results of ZIKV in Ago2 knockout versus Dcr2 knockout cells, as recent results have shown that virus infection is unable to induce Vago expression in Ae. aegypti-derived cells." (PMID 34205194, 2021). "Besides, the differences in hierarchy in the exo-siRNA pathway and additional protein interaction of Dcr2 and Ago2 could also explain, at least partly, the differences seen for the different knockout cells upon virus infection." (PMID 34205194, 2021). "Thus, we designed an in vitro slicing assay using three synthetic single-stranded RNAs as the slicing target to determine whether the vsiRNAs made by adult mice in response to viral infection are active to guide specific RNA slicing by Ago2 in RISC." (PMID 32753500, 2020). "Since overexpression of Dcr2 and Ago2 resulted in an improved survivorship to the acute infection of CrPV, we checked whether this approach would result in decreased levels of a persistent viral infection." (PMID 29403066, 2018). "With a viral infection, the RNAi machinery’s activity could be enhanced to combat the infection, for example, through the upregulation of the core components Dcr-2, R2d2, and Ago-2." (PMID 30687121, 2018).
viral infection (continued). "To determine whether the viral-encoded RNAs are selectively sorted and if the sorting system is affected by viral infection, we compared the content of deep-sequenced RNA extracted from immunoprecipitation (IP) experiments with the Ago1 and Ago2 proteins using EBV-infected cells." (PMID 24627180, 2014). "Taken together, our findings support the notion that nuclear localization of AGO2 acts as a mechanism to suppress the induction of antiviral type-I IFN and their signaling cascade, thereby facilitating viral infection." (PMID 40219968, 2025). "In addition, AGO2 confers resistance to viral replication and could be a therapeutic candidate for viral infection and our data showed that the expression of AGO2 was higher in the LDGs than the NDGs and the expression of AGO2 was down‐regulated by the incubation with SARS‐CoV‐2 in LDGs." (PMID 36271697, 2023). "On the contrary, viral infection stimulated up-regulation of DCL2, AGO2, and RDR1 in self-grafted UC and of DCL2, AGO2 and RDR6 in the UC/Ma graft combination." (PMID 32824316, 2020). "In this study, we investigated the roles of DCL2, DCL4, AGO2, AGO3 and RDR6 in tomato responses to viral infection." (PMID 33032637, 2020). "In G. pallidipes, the model Glossina species in this study, the siRNA pathway genes AGO2 and DCR2 were upregulated during virus infection, which confirmed the involvement of the RNAi response in the flies’ defense against GpSGHV." (PMID 30470195, 2018). "In mosquitoes variations in levels of Ago2, DICER2 and other components of RISC were observed during virus infection, indicating that the virus can modulate the RNAi system." (PMID 24391886, 2013). "The observed co-precipitation of RIG-I and AGO2 in mock-infected cells suggests a potential interaction between these two proteins in the absence of viral infection." (PMID 40949099, 2025). "Consistently, our study also revealed the altered expression of GAPDH, AGO2, and actins upon viral infections, suggesting that these are not suitable as reference genes in studies of viral infection." (PMID 36840204, 2023). "The accumulation of AGO2 mRNA may be induced by the reduction of miR403, which depends on the suppression of the AGO1 function by virus infection." (PMID 35891562, 2022). "Taken together, these results show that the basal levels of Dcr-2 and Ago-2 do not play a critical role in fly survival and in the control of viral infections." (PMID 32194567, 2020). "A single strand of the siRNA duplex is loaded into the Argonaute-2 (Ago2)-containing RNAi Induced Silencing Complex (RISC), which then slices any viral sequence that is complementary to the loaded siRNA, thereby controlling virus infection." (PMID 29522475, 2018). "Therefore, this newly revealed mechanism shows that cellular response leads to transfer of AGO2 from cell nucleus and promotes IFN-β expression to increase host survival during viral infection." (PMID 28589097, 2017). "Interestingly, AGO2 and SCP-2 showed a correlation between their levels of expression and DENV load, which reaffirms that they play a role in the viral infection." (PMID 29282144, 2017). "During virus infection, the decrease in the translation of AGO1 protein leads to accumulation of AGO2, due to the absence of AGO1-miR403-mediated posttranscriptional down-regulation of AGO2." (PMID 27711201, 2016). "UV Ago2 RIP assay shows that the binding of Ago2 to DDX5 in cells overexpressing mimic-miR-NS during JEV/WNV infection was considerably less than that of mock-infected cells transfected with mimic-miR-NS; this is likely due to the downregulation of miR-1-3p during viral infection." (PMID 40272157, 2025).
viral infection (continued). "In addition, the known cytoplasmic function of AGO2 in antiviral RNAi suggests that AGO2 nuclear sequestration by IAV-WSN NS1 may promote virus infection." (PMID 33281788, 2020). "As we did not observe a correlation between Dcr-2 and Ago-2 proteins basal levels and infection outcomes in the D. melanogaster strains tested, we wanted to explore if a difference in gene expression would be noticeable as a result of the viral infection." (PMID 32194567, 2020). "However, the normal life span and the lack of elevated expression of known virus infection-responsive genes such as Vago, AGO2 or Sting in lincRNA-IBIN OE flies argues against a non-specific viral response." (PMID 30633769, 2019). "The significance of AGO2-dependent gene regulation for virus infection, if any, is not yet clear." (PMID 25806948, 2015). "However, unlike in Arabidopsis where AGO2 gets induced during viral infections, there is hardly any change in AGO2 levels during Rice stripe virus and Rice dwarf virus infections in rice." (PMID 25443390, 2014). "In our work we showed that the key components of the antiviral siRNA pathway in D. melanogaster, Dcr-2 and Ago-2, are not induced at the mRNA level upon viral infection, but that their regulation occurs at the protein level through an unknown mechanism reminiscent of translation on demand." (PMID 32194567, 2020). "RNAi-mediated knock-down of ago-2, dcr-2 and to a lesser extent, the RISC component Tudor staphylococcal nuclease (TSN), resulted in enhancement of viral infection by feeding but did not affect mortality." (PMID 31354527, 2019). "In both the experimental conditions either DENV virus infection or DENV NS5 overexpression, no substantial change was observed in Dicer, Drosha, or AGO2 protein expression levels." (PMID 32123831, 2019). "Although overexpression of Dcr2 and Ago2 did not induce obvious changes in the mlv transcript levels, the question whether virus-specific siRNAs can directly interact with the RNAi machinery to eventually play a role in the defense against persistent viral infections remains unanswered." (PMID 29403066, 2018). "In contrast, AGO2 remained cytoplasmic in TP53L MCF7 cells, irrespective of viral infection load." (PMID 40219968, 2025).
breast carcinoma (76 papers, 2009 to 2026). "Conversely, AGO3 was consistently found to be associated with AGO2 in the nucleus of the human breast cancer cell line T47D." (PMID 38133208, 2023). "The impact of AGO2 SNPs on disease susceptibility has also been assessed in breast cancer by different research groups." (PMID 33668654, 2021). "Based on the analysis of 488 breast cancer specimens, Sung and colleagues depicted that two AGO2 genetic variants, rs11786030 A/G and rs2292779 C/G, were correlated with elevated risk of breast cancer." (PMID 33668654, 2021). "It will be interesting to demonstrate if Ago2 is implicated in miR-615-3p-mediated PICK1 repression in breast cancer cells." (PMID 32336285, 2020). "The aim was to define Ago2 expression (mRNA and protein) and localisation in breast cancer, and investigate associations with clinicopathological details." (PMID 31324173, 2019). "Testing the association between Ago2 staining intensity and breast cancer subtype, there is evidence to suggest a general association in the population (p ≈ 0.000)." (PMID 31324173, 2019). "Testing the association between Ago2 staining intensity and breast cancer receptor status, there is evidence to suggest a general association between the Estrogen Receptor (ER) and Ago2 staining in the population (p ≈ 0.000)." (PMID 31324173, 2019). "Conversely, SNP rs3864659 (A > C) in AGO2 protected against breast cancer risk (OR = 0.67; CI 0.46–0.96) in a Korean population, as observed by a case-control study involving 559 breast cancer cases vs. 567 controls." (PMID 30897768, 2019). "In breast cancer, single-nucleotide polymorphisms of Ago2 have been associated with changes in disease free survival (DFS) and overall survival (OS)." (PMID 31324173, 2019). "AGO2 gene expression strongly correlated with the more aggressive and invasive basal-like breast cancer phenotypes and was inversely associated with ERα status." (PMID 29657266, 2016). "Among ERα+ tumor types, loss of PGR expression correlates with aberrant estrogen signaling, and we show that AGO2 expression in an ERα+ breast cancer cell line can repress classical ERα signaling (loss of ERα expression and loss of E2 stimulation of PGR)." (PMID 29657266, 2016). "MCF-7 breast cancer cells overexpressing AGO2 (MCF7-AGO2) altered ERα downstream signaling and selective ERα variant expression." (PMID 29657266, 2016). "For instance, three SNPs, i.e. rs3864659, rs2292779 and rs11786030, in the AGO2 gene were shown to be associated with breast cancer in Korea population." (PMID 26545861, 2015). "Materials and methods: Realtime PCR is used to validate the presence of mRNA encoding P-glycoprotein (P-gp) and Argonaute 2 (Ago2) in MPs isolated from drug resistant human breast cancer cells (MCF-7/DX)." (PMID 26082317, 2013). "In our previous study, we reported SNP rs3864659 in AGO2 is associated with the reduction of breast cancer risk." (PMID 22639842, 2012). "Further studies on the influence of AGO1 and AGO2 SNPs on breast cancer susceptibility were conducted on 93 Mediterranean cases and uncovered another AGO1 SNP (rs636832 A/A), as well as one more AGO2 (rs2977490 G/G) variant associated with elevated risk of the disease." (PMID 33668654, 2021). "Indeed, there is increasing evidence that the genetic variants in the AGO2 gene are associated with the risk or development of several cancers, including breast cancer and malignant peripheral nerve sheath tumor." (PMID 26545861, 2015). "The AGO2 rs2292779 was also associated with poor prognosis of breast cancer." (PMID 22639842, 2012). "Ago2 is overexpressed in certain types of cancer, such as breast cancer, colorectal cancer, ovarian cancer, gastric cancer, and glioma." (PMID 38649663, 2024).
breast carcinoma (continued). "Luciferase-labeled HCC1806 Ago2-KO/AID-Ago2Wt/Ago2∆ breast cancer cells were injected into the fat pads of SCID mice, which were then continuously treated with PBS or IAA for 2 weeks." (PMID 38649663, 2024). "In primary breast carcinomas, Ago2 was distributed in the entire tumor cells, both in the nuclei and in the cytoplasm (Fig. EV4Aiii)." (PMID 38649663, 2024). "Knockdown of Ago2 in a MCF7 CD95 k.o. breast cancer cell line attenuated CD95L mRNA toxicity, supporting our observations in HeyA8 CD95 k.o. cells." (PMID 37059938, 2023). "While knockdown of Ago2 in ovarian and breast cancer cell lines blocked toxicity by CD95L mRNA, knockdown or knockout of Ago2 did not rescue DISE induced by either CD95L mRNA or toxic seed containing shRNAs in the colon cancer cell line HCT116." (PMID 37059938, 2023). "The RIP assay indicated the binding between circTBPL1 and AGO2, which is essential for the biogenesis and function of miRNAs, supporting the potential of circTBPL1 as a miRNA sponge in breast cancer." (PMID 37495592, 2023). "In other contexts, miR-145-5p induces post-transcriptionally Ago2 expression, dictating miR-145-5p tumor suppressor activity (breast carcinoma cell lines)." (PMID 34991639, 2022). "In this study, we explored the down-modulation of AGO2 in breast cancer treated with UA, which led us to understand the increase in the level of PTEN inversely associated with AGO2 expression in inhibiting breast cancer invasiveness." (PMID 36613808, 2022). "In the present study, UA suppresses CSC and EMT to alleviate metastatic phenotypes by inhibiting AGO2 in breast cancer cell lines." (PMID 36613808, 2022). "Analysis of gene expression data derived from The Cancer Genome Atlas and 291 breast cancer specimens pointed to a correlation of high expression of AGO2 with unfavorable, hormone receptor-positive, subtypes of disease, and poor clinical outcome." (PMID 33668654, 2021). "For example, it has been reported that ERα directly inhibits Drosha and that Exportin 5, Dicer1, Ago1, and Ago2 are low in ERα positive breast cancers." (PMID 33477993, 2021). "Other studies have reported that in human neuroblastoma, fibroblast and breast cancer cells, AGO2 can shuttle microRNA from the cytoplasm into the nucleus in order to bind to the targeted gene promoter region as an AGO2-microRNA complex." (PMID 34201585, 2021). "We thus performed RIP assay and found that circMETTL3 was enriched in AGO2 immunoprecipitates in breast cancer cells." (PMID 33867838, 2021). "Single-Nucleotide Polymorphisms (SNPs) of AGO1 and AGO2 genes were found to be related to Disease-Free Survival (DFS) and Overall Survival (OS) in breast cancer in order to risk impact of renal cell carcinoma." (PMID 32503341, 2020). "Abnormal overexpression of AGO2 has been found in several human tumors, including breast cancer, urothelial carcinoma of the bladder, glioma, and nasopharyngeal carcinoma." (PMID 32420319, 2020). "To better understand the LASP1-Ago2 interaction we wanted to identify motility-related protein targets of Ago2 that are upregulated in breast cancer." (PMID 32872485, 2020). "More specifically, AGO2 rs3864659 presents a protective effect on breast cancer patients whereas AGO2 rs11786030 and rs2292779 have been linked to a poor prognosis in Korean cohorts." (PMID 32503341, 2020). "The current study demonstrated the attenuated interaction between miR-221/222 and p27 and decreased Ago2 expression by starvation-induced stress in MDA-MB-231 breast cancer cells." (PMID 32631271, 2020). "Clinical data from breast cancer patients unveil a link between AGO2 phosphorylation at Tyr393 and poor overall survival." (PMID 32503341, 2020). "We found that knowing Ago2 protein levels in tumour improves the ability to predict breast cancer subtype (by 20%), which is related Ago2 staining improving the ability to predict Estrogen or Progesterone receptor status (by 15.7 and 17.5% respectively)." (PMID 31324173, 2019).